SLC2A1 (solute carrier family 2 member 1)
Diseases named in the same sentence as SLC2A1 in open-access papers (continued):
Sharing a sentence is not in itself a finding about the gene and the disease.
tumor (1,633 papers, 2002 to 2026). "The expression level of SLC2A1 is also associated with tumor staging, and the later the tumor stage, the higher the expression of SLC2A1." (PMID 41003841, 2025). "The findings showed a significant suppression of tumor growth in the SLC2A1-deficient group compared to the control group, with tumor size and weight being significantly lower (P < 0.01)." (PMID 40824962, 2025). "The Glut1-encoding gene Slc2a1 was predominantly expressed in tumor cells, whereas the Glut3-encoding gene Slc2a3 was expressed weakly in tumor cells but strongly in immune cells, particularly myeloid cells." (PMID 39545407, 2024). "Deletion of SLC2A1 in tumor-associated neutrophils hampers lung tumor growth and enhances radiotherapy efficacy." (PMID 38831301, 2024). "Consistent with prior results, we found that tumor cells mostly expressed the Glut1-encoding gene Slc2a1, whereas myeloid cells predominantly expressed Slc2a3." (PMID 39545407, 2024). "Hypoxia-associated macrophages (Mac_Hypo, n = 1802) were mostly found in tumor samples (lung and ovary) and presented an enrichment of genes associated with hypoxia, such as SLC2A1 and ERO1." (PMID 38972873, 2024). "Among the many genes associated with glucose metabolism, SLC2A1 is the gene encoding a glucose transporter protein that controls glucose uptake and plays a key role in the growth and proliferation of tumor cells." (PMID 36782138, 2023). "The results of the analysis using UCSCXenaShiny, however, showed that the CNA species of SLC2A1 was strongly associated with tumor prognosis in a wide range of cancers." (PMID 36712872, 2022). "The results of the tumor immune cell infiltration analysis showed that SLC2A1 was significantly associated with multiple immune cell infiltrations in a variety of cancers." (PMID 36712872, 2022). "SLC2A1 expression was correlated with clinical staging in 11 cancers, which indicated that SLC2A1 was associated with tumor progression." (PMID 36712872, 2022). "Overexpression of SLC2A1 is associated with many tumor features, including increased invasion, increased proliferative activity, and decreased survival." (PMID 35517408, 2022). "Another well-established HIF-1α target that contributes to a tumor cell’s high rate of glucose uptake is the glucose transporter 1, GLUT1 (encoded by the SLC2A1 gene)." (PMID 35328229, 2022). "SLC2A1, the gene encoding GLUT1, plays an important role in tumorigenesis and tumor progression of various cancer, which is closely related to glycolysis." (PMID 34520391, 2021). "We considered 15 tumor types for which more than five patients carried a mutation in one of the P2X7 proteins or the SLC2A1 gene." (PMID 29855388, 2018). "SLC2A1, for instance, is critical for the growth and proliferation of tumor cells, with high SLC2A1 expression being associated with increased migration and poor patient survival." (PMID 28640862, 2017). "Here, we show that loss of one or both alleles of Slc2a1 from mammary epithelial cells expressing the active Neu oncogene prevented tumor formation." (PMID 27998284, 2016). "DERL3 loss leads to SLC2A1 (glucose transporter 1, GLUT1) overexpression, which contributes to the Warburg phenomenon of tumor cells." (PMID 27359056, 2016). "SLC2A1 overexpression has been linked to transporting more glucose across the cell membrane and allowing for the continuation of aerobic glycolysis and the cell cycle, aiding tumor cell proliferation." (PMID 40563443, 2025). "Moreover, SLC2A1 expression was strongly linked to immune infiltration and regulation across different tumor types." (PMID 40824962, 2025). "GO and KEGG pathway enrichment analyses further confirmed that key biological processes involved in high SLC2A1 expressing cells may be closely linked to tumor energy metabolism and cell proliferation." (PMID 39992528, 2025).
tumor (continued). "Interestingly, the marker genes in the hypoxic subpopulations were previously shown to be associated with tumor progression, such as SLC2A1 and VEGFA in H1 subpopulation." (PMID 37441593, 2023). "Moreover, HK2, MMP11, CDH3, PDK4, SERPINB5, and SLC2A1 expression were closely associated with tumour stages." (PMID 37234801, 2023). "In LUAD and HCC, SLC2A1 plays a significant prognostic role and is associated with tumor immunity." (PMID 36275774, 2022). "We suggest that the promoting effect of SLC2A1 on CRC may be associated to the mechanism of ferroptosis of tumor cells." (PMID 35399515, 2022). "We analyzed the expression of SLC2A1 in different cancers and the association between its expression and cancer prognosis, immune cell infiltration, immune-related marker expression, and tumor functional status." (PMID 36712872, 2022). "However, the mechanisms underlying the relationship between the CNV status of SLC2A1 and tumor prognosis are still unclear, and the paradoxical results exhibited in LUAD in particular deserve further investigation." (PMID 36712872, 2022). "Finally, SLC2A1 positively associated with neutrophils and cancer-associated fibroblasts in the tumor microenvironment of most cancers and significantly correlated with TMB and MSI in various cancers." (PMID 36358765, 2022). "As elevated SLC2A1 is closely associated with depth of invasion and clinical stage, we hypothesized that over-expression of SLC2A1 may facilitate tumor cell invasion and further contribute to distant metastasis." (PMID 26193257, 2015). "ST confirmed Man-Alb enrichment in extracellular matrix (ECM)/TAM-rich clusters (mannose receptor C-type 1, Mrc1-high) and Gal-/Glc-Alb uptake in glycolytic/hypoxic tumor clusters (Slc2a1-high)." (PMID 41355949, 2026). "SLC2A1 expression was higher in stages 2, 3, and 4 than in stage 1, suggesting a link to poor tumor prognosis." (PMID 40276602, 2025). "Using SLC2A1 overexpression in tumors, SLC2A1 expression combined with imaging techniques such as FDG-PET can assess tumor metabolism and predict patient outcomes." (PMID 40362545, 2025). "High expression of SLC2A1 promotes increased glucose uptake required for tumor growth and survival under hypoxic conditions." (PMID 40362545, 2025). "Colony formation assays and Transwell assays revealed that high expression of SLC2A1 promoted tumor migration." (PMID 40092704, 2025). "Expression of multiple amino acid transporters on the tumor cell surface is downregulated upon tumor cell growth in spheroids while expression of the glucose transporter Slc2a1 is upregulated, suggesting more efficient glucose uptake." (PMID 40589546, 2025). "New imaging probes such as WZB117-IR820 targeting SLC2A1 are now being developed to enhance early detection and complete tumor resection." (PMID 40362545, 2025). "Upregulated SLC2A1 in LIHC tumor tissue is correlated with the clinical stage and prognosis of patients." (PMID 40662145, 2025). "Our analysis highlights the importance of genes like SLC2A1, which regulates glucose metabolism and correlates with tumor invasiveness and poor prognosis." (PMID 39992528, 2025). "Tunel staining demonstrated that knockdown of RP11-544M22.13 significantly increased the apoptosis levels of tumor cells, whereas overexpression of SLC2A1 decreased it." (PMID 41309566, 2025). "The correlation between SLC2A1 and the Stromal, Immune, and ESTIMATE scores of various tumors, including LUAD, was analyzed to evaluate the relationship between SLC2A1 and the tumor microenvironment and immune infiltration." (PMID 40824962, 2025). "This study delved further into the correlation between SLC2A1 expression and the tumor microenvironment." (PMID 40824962, 2025). "The relationship between SLC2A1 expression as well as tumor immune infiltration and immune checkpoint molecules, was also determined." (PMID 40824962, 2025).
tumor (continued). "This visual separation validates that the expression level of SLC2A1 can effectively distinguish between different cell populations, suggesting its potential role in cell differentiation and tumor heterogeneity." (PMID 39992528, 2025). "Specifically, SLC2A1 is overexpressed in the tumor tissues of UCEC patients, and MPST also exhibits a high level of expression in these tissues." (PMID 40746529, 2025). "Statistical analysis revealed significant co-localization between the dominant barcode and SLC2A1 expression in the recurrent tumor." (PMID 41000875, 2025). "PGK1 and SLC2A1 plays an important role in this phenomenon to promote the increased glycolytic rate of tumor cells." (PMID 40821990, 2025). "The findings indicated that elevated levels of SLC2A1 were closely associated with the malignant progression of LUAD, significantly enhancing tumor cell proliferation, migration, and invasion." (PMID 40824962, 2025). "We found mean SLC2A1 mRNA expression to be the highest in HNSCC among tumor subtypes and the fourth highest among cancer cell line subtypes." (PMID 40371988, 2025). "We identified genes enriched in persister subpopulations and spatially mapped a dominant resistant clone marked by SLC2A1 expression in the resistant tumor." (PMID 41000875, 2025). "Our study further reveals that epithelial cells with high SLC2A1 expression are more prevalent at the tumor margins and metastatic sites, suggesting their potential critical role in tumor dissemination and metastasis." (PMID 39992528, 2025). "Proliferation assays indicated that knockdown of SLC2A1 inhibited the proliferation capacity of tumor cells." (PMID 40092704, 2025). "Using RNAscope fluorescent multiplex assay, we spatially mapped a dominant persister subpopulation (top 3 barcode, 7.5% of recurrent tumor) and quantified the co-occurrence of the stress-like marker SLC2A1." (PMID 41000875, 2025). "Analysis of the TCGA database revealed significant differences in SLC2A1 (GLUT1) expression between tumor and normal tissues across various cancers." (PMID 40276602, 2025). "Tunel staining showed that overexpression of RP11-544M22.13 significantly reduced the apoptosis level of tumor cells, while knockdown of SLC2A1 increased the apoptosis level of tumor cells." (PMID 41309566, 2025). "Deletion of SLC2A1 significantly inhibited tumor growth compared to the control, accompanied by a significant reduction in Ki67 expression and cellular proliferation." (PMID 40824962, 2025). "Our experiments also demonstrate that SLC2A1 functions as an oncogene by promoting tumor cell proliferation, migration, and invasion." (PMID 39992528, 2025). "The hub genes of the network included SLC2A1 (solute carrier family 2 member 1), CDH3 (cadherin 3), and EFHD2 (EF-hand domain family member D2), whose expression increased with tumor stage and was associated with a lower survival rate." (PMID 39199659, 2024). "Upregulation of glucose transporter protein expression, especially SLC2A1 and SLC2A3, is a hallmark of tumor metabolic reprogramming." (PMID 38831301, 2024). "In this model, logistic regression analyses demonstrated that clinical parameters (age, gender, and tumor stage) and core molecules (SLC2A1, TLE1, FAM83A, HMGA2, FBXO44, and MTRNR2L12) contributed differently to LUAD scores at different stages." (PMID 38338834, 2024). "In the end, the role of SLC2A1 in tumor dynamics was examined using RT-PCR, immunohistochemistry, CCK-8, wound healing, and transwell tests." (PMID 39669580, 2024). "SLC2A1 had a distinct distribution, being less enriched in tumor regions, and instead favoring regions with blood vessels." (PMID 39678375, 2024). "Of the genes that were significant, only SLC2A1 had a higher gene expression in the tumor samples than in adjacent-normal samples." (PMID 39678375, 2024). "For example, KD of the main glucose importer, SLC2A1, was deleterious in A375 cells in all tested conditions, while OE enhanced tumour growth." (PMID 38605144, 2024).
tumor (continued). "Thus, SLC2A1 may be a diagnostic and prognostic biomarker in CC related to tumor blood supply." (PMID 39678375, 2024). "Researchers have found that SLC2A1 promotes glycolysis in tumor cells, thus promoting their proliferation, invasion, and migration of tumor cells." (PMID 39526479, 2024). "For instance, the advantage conferred by SLC2A1 OE in A375 tumours indicates that glucose is probably limiting proliferation of A375 cells in that environment." (PMID 38605144, 2024). "Specifically, the expression of SLC2A1 in tumor tissues exhibited a remarkable increase, whereas the expression of TXNIP demonstrated a noteworthy decrease." (PMID 39526479, 2024). "Downregulation of SLC2A1, identified through this approach, showed promise in suppressing tumour growth, offering a potential therapeutic avenue." (PMID 39190283, 2024). "AHNAK2 and SLC2A1 were primarily expressed in epithelial cells, while CD27 and LTB were predominantly associated with T cells, potentially influencing tumor immunity." (PMID 39593730, 2024). "Specifically, MMP9, MMP13, MMP11, and CEMIP were positively associated with the tumor immune microenvironment, while SLPI, SLC2A1, SERPINB5, HK2, CEACAM6, and CEACAM5 were negatively associated with the tumor immune microenvironment." (PMID 37234801, 2023). "The unlimited capacity of tumor cells for growth and proliferation requires an adequate amount of energy; therefore, SLC2A1 is upregulated in many tumors." (PMID 36936141, 2023). "The essentiality of IGSF3 and SLC2A1 in a significant fraction of HNSC cell lines testifies to their importance to the viability of HNSC tumor cells." (PMID 37835579, 2023). "The growth of tumor cells treated with an anti-SLC2A1 short hairpin RNA (shRNA) is markedly suppressed." (PMID 37545500, 2023). "In our experiment, both PDT treatment of Se-PC and PC downregulated the gene expressions of S100a9, Slc2a1, and Lcn2 to slow tumor proliferation by regulating cell metabolism and iron binding." (PMID 37994159, 2023). "Lastly, the in vivo effect of BMP4-regulated SLC2A1 on HCC tumor growth was assessed in a xenograft model of HCC." (PMID 37443106, 2023). "In particular, we identified a specific signature of glycolysis-related genes in BRAF-like tumours, which display the overexpression of SLC2A1, SLC2A3, HK3, PFKFB3, PKM, LDHA and SLC16A3 (alias Mct4, the membrane channel regulating lactate efflux)." (PMID 37198319, 2023). "SLC2A1 inhibits oxidative phosphorylation and enhances cellular glycolysis, helping tumor cells to adapt to their hypoxic microenvironment." (PMID 36936141, 2023). "This study further showed that SLC2A1 can promote tumor cell growth by activating glycolysis-related pathways in different cancer species." (PMID 37576511, 2023). "The correlation of SLC2A1 with the efficacy of immune checkpoint blocker (ICB) therapy was evaluated using the tumor immune dysfunction and exclusion (TIDE) score." (PMID 36712872, 2022). "The protein expression levels and phosphorylation of SLC2A1 in normal and primary tumor tissues were compared in UALCAN using CPTAC data." (PMID 36712872, 2022). "In PDAC patient samples we also detected strong IHC staining of SLC2A1 primarily in tumor cells, which was positively correlated with USP25 protein expression." (PMID 35440539, 2022). "Among the data from four tumor types with SLC2A1 phosphorylation information included in CPTAC, we found a decreased S490 phosphorylation in BRCA, increased T234 phosphorylation in HNSC, and increased T234 phosphorylation in KIRC." (PMID 36712872, 2022). "SLC2A1 IHC scores in tumor tissues were remarkably higher than those in paracancerous tissues (2.375 ± 0.606 vs. 0.896 ± 0.592)." (PMID 35399515, 2022). "The correlation of SLC2A1 with tumor biological function was evaluated at the single-cell level using the CancerSEA database." (PMID 36712872, 2022). "The high expression of SLC2A1 accelerates the glucose uptake of tumor cells and provides sufficient raw materials for glycolysis." (PMID 35517408, 2022).
tumor (continued). "We calculated the correlation between SLC2A1 and tumor microenvironment using the TCGA pan-cancer dataset." (PMID 36358765, 2022). "To further explore the relationship between SLC2A1 and tumor immunity, we analyzed the correlation between SLC2A1 and immune-related markers on TISIDB." (PMID 36712872, 2022). "As a primary switch of aerobic glycolysis, GLUT1 is also known as the solute carrier family 2 member 1 protein SLC2A1, involving in tumor survival and metastasis." (PMID 36476606, 2022). "This suggests that the type of CNA alteration in SLC2A1 can be used as a generalized tumor prognostic predictor." (PMID 36712872, 2022). "A lower differentiation grade tumor is implied by overexpression of SLC2A1, SLC2A5, SLC2A10, SLC2A11and lower levels of SLC2A3, SLC2A6, SLC2A9, SLC2A12, and SLC2A14, emphasizing the possibility of these molecular roles for predicting the course of the tumor." (PMID 36518662, 2022). "Targeting SLC2A1 or GLUT1 has been shown to result in significant inhibition of tumor effects in both cell and animal studies of multiple tumors." (PMID 36057597, 2022). "LUAD tumor tissues showed higher mRNA expressions of SLC2A1, SLC2A5, and SLC2A12 and lower expressions of SLC2A3, SLC2A4, SLC2A6, SLC2A9, and SLC2A14." (PMID 36518662, 2022). "We explored the SLC2A1 genetic alterations in human tumor samples via the cBioPortal tool, using the TCGA Pan-Cancer dataset to complete this analysis." (PMID 36712872, 2022). "The CancerSEA database was applied to explore the relationship between SLC2A1 expression and biological functions commonly involved in tumor occurrence and development in pan-cancer at the single-cell level." (PMID 36712872, 2022). "As miR-199a was proved effectively inhibit the development of tumor, the mRNA expression of SLC2A1 was tested in the tumor samples from plenti/plenti-miR-199a mouse models which were five in number respectively." (PMID 35517408, 2022). "Our results comprehensively revealed the potential mechanism of SLC2A1 in pan-cancer, and they highlight the impact of SLC2A1 on the tumor microenvironment (TME) and cancer immunotherapy." (PMID 36358765, 2022). "The ROC curve indicated that SLC2A1 had high accuracy in predicting the outcomes of normal and tumor, and the area under the ROC curve was 0.901 (95% CI: 0.869–0.934)." (PMID 35399515, 2022). "The results showed a certain correlation between SLC2A1 and immune modulators in all 33 tumor types." (PMID 36358765, 2022). "We found that there are a lot of methylation sites in SLC2A1 and that the methylation of SLC2A1 is correlated with the immunosuppression of tumor tissue." (PMID 36065306, 2022). "Firstly, we used the XCELL algorithm to score the immune infiltration of all TCGA Pan-Cancer samples and calculated the correlation between SLC2A1 expression and 36 different immune infiltrating cells and tumor microenvironment scores in each cancer." (PMID 36712872, 2022). "SLC2A1 has a large number of methylation sites, and the methylation of SLC2A1 is related to T cell exhaustion and immunosuppression in tumor tissue." (PMID 36065306, 2022). "Many studies have pointed out that SLC2A1 plays a key role in mediating the regulation of tumor energy metabolism, indicating that it is a pivotal potential target in tumor therapy." (PMID 35517408, 2022). "We found that there are abundant methylation sites in SLC2A1 and that the methylation of SLC2A1 is correlated with the immunosuppression of tumor tissue." (PMID 36065306, 2022). "The median expression of SLC2A1 in tumor and normal samples in a body map from GEPIA2.0 was also displayed." (PMID 36712872, 2022). "The SLC2A1 expression in CRC was closely correlated with tumor stage and progression free interval (PFI)." (PMID 35399515, 2022). "According to data from the UALCAN database, LUAD patients’ tumor tissues had hypomethylation of SLC2A1, SLC2A2, SLC2A5, SLC2A6, SLC2A7, SLC2A11 and hypermethylation of SLC2A3, SLC2A10, and SLC2A14 compared to normal tissues." (PMID 36518662, 2022).